CRYAB (crystallin alpha B)
Diseases named in the same sentence as CRYAB in open-access papers (continued):
Sharing a sentence is not in itself a finding about the gene and the disease.
oligodendroglioma (1 paper, 2021). A well-differentiated (WHO grade II), diffusely infiltrating neuroglial tumor, typically located in the cerebral hemispheres. "Finally, we observed a higher level of APOE, BMP4, KCNN3/SK3, and CRYAB proteins in astrocyte-like cells, whereas the IDH1 enzyme appears to be more expressed in oligodendrocyte-like cells in oligodendroglioma." (PMID 33925547, 2021).
optic atrophy (1 paper, 2024). A disorder characterized by loss of optic nerve fibers. "CRYAB encoding a highly conserved protein acting as mitochondrial chaperone and possessing anti-apoptotic activities is the molecular component of retinal ganglion cells, which its dysfunctions led to defects in ganglion neurons and caused optic atrophy." (PMID 39561005, 2024).
Oral Cancer (1 paper, 2011). "In order to understand the genomic role of CRYAB in oral cancer, we have chosen three single nucleotide polymorphisms (SNPs) of CRYAB, A-1215G (rs2228387), C-802G (rs14133), intron 2 (rs2070894), and investigated their genotypic distribution in a large Taiwanese oral cancer population." (PMID 21915251, 2011). "In 2005, it is reported that CRYAB was down-regulated at mRNA level from oral cancer patients compared with normal oral mucosa." (PMID 21915251, 2011). "In previous literature, it was reported that CRYAB was significantly over expressed in the primary tissue from oral cancer patients in Taiwan." (PMID 21915251, 2011). "On the contrary, it was reported that from a proteomics screening in Taiwan, CRYAB was significantly up-regulated in the primary tissue from oral cancer patients." (PMID 21915251, 2011). "It has recently been recognized that CRYAB protein may play a role in oral cancer development." (PMID 21915251, 2011).
prostate adenocarcinoma (1 paper, 2020). "CRYAB, an HSP20 member, inhibited cell proliferation while inhibiting EMT in 14 cancers, including BRCA, LUAD, and prostate adenocarcinoma (PRAD)." (PMID 33225964, 2020).
renal clear cell carcinoma (1 paper, 2022). "To detect CRYAB expression in KIRC and Caki-1, we collected the specimens of renal clear cell carcinoma and their adjacent noncancerous tissues and cultured Caki-1 and HK-2 for RT-qPCR." (PMID 36713654, 2022).
skin cutaneous melanoma (1 paper, 2022). "The forest plots showed that the CRYAB gene was a risk factor in BLCA, COAD, and OV, but a protective factor in KICH, LGG, PRAD, and skin cutaneous melanoma (SKCM)." (PMID 36713654, 2022).
stomach adenocarcinoma (1 paper, 2019). "In the stomach adenocarcinoma dataset, strong positive correlations in gene expression were identified between members of the small HSP family, including HSPB2, HSPB5 (CRYAB), HSPB6, HSPB7 and HSPB8, as well as the HSP40 family member DNAJB5, with superoxide dismutase (SOD3)." (PMID 30578123, 2019).
triple-negative breast carcinoma (1 paper, 2021). An invasive breast carcinoma which is negative for expression of estrogen receptor (ER), progesterone receptor (PR), and human epidermal growth factor receptor 2 (HER2). "Our results are consistent with previous studies that demonstrate high HSP27 expression is linked to ER and PR expression and high CRYAB is linked to basal and triple negative breast cancer (TNBC; ER-/ PR−/HER2−;)." (PMID 35235182, 2021).
Type 1 diabetes (1 paper, 2022). "For example, some of the most significantly altered MAM proteins in our Type 1 diabetes model included LGALS3, GPX4, PDGFR, AQP4, and alphaA- and alphaB-crystallin (CRYAA and CRYAB)." (PMID 36139394, 2022).
viral myocarditis (1 paper, 2017). Myocarditis that is caused by an infection with a viral agent. "In summary, our studies not only provide novel insights into the pathogenic mechanisms of viral myocarditis, but also offer an excellent model system to understand the regulation and function of CryAB in other heart diseases." (PMID 29088822, 2017). "In this study, we investigated the regulation and functional role of CryAB in CVB infection and viral myocarditis." (PMID 29088822, 2017).
tumor (63 papers, 2007 to 2025). "In a wide variety of tumor types CRYAB has been found to be overexpressed and associated with disease progression and poor prognosis." (PMID 30310055, 2018). "Conversely, only four of the thirteen deletions that resulted in a significant decrease in expression in tumors were previously identified as down-regulated when comparing normal and tumor tissue (CRYAB, SACS, HSPB7, and HSPB2)." (PMID 38816397, 2024). "CRYAB is a critical element of the tumor microenvironment, positively correlated with immune checkpoints, tumor mutational burden, and influencing tumor prognosis in human cancers." (PMID 38971757, 2024). "Within these networks, we found that these four TFs regulated multiple tumor-specific genes, such as FXYD2 and CRYAB, with a significant increase in expression in tumor cells." (PMID 35853872, 2022). "Current studies show that the CRYAB gene is an oncogene, and patients with high expression of CRYAB are in the advanced tumor stage or have a poor prognosis." (PMID 36713654, 2022). "Although there has been evidence of CRYAB's effect on tumor prognosis and tumor-infiltrating lymphocytes, it has only been limited to a few tumors, and there has been no comprehensive pan-cancer analysis based on TCGA and GO." (PMID 36713654, 2022). "Lastly, since highly downregulated DEGs such as PLAU, CTGF and CRYAB are known to promote angiogenesis in cancer, the in vivo tumor-suppressive effects of MARK3 were investigated via a mouse xenograft experiment using MARK3-inducible OVCAR3 cells." (PMID 35017636, 2022). "There is evidence that the Crystallin Alpha B (CRYAB) gene is involved in the regulation of the tumor microenvironment and influences tumor prognosis in some cancers." (PMID 36713654, 2022). "Recent studies have confirmed that the CRYAB gene regulates tumor invasion and metastasis in colorectal cancer and gastric cancer." (PMID 36713654, 2022). "CRYAB induced lung metastasis in vivo, in which inhibition of CRYAB reduced tumor size through the MEK/ERK signaling pathway." (PMID 36077137, 2022). "Collectively, these studies highlight CryAB as a potential therapeutic to decrease tumor progression." (PMID 34831344, 2021). "Down-regulation of CRYAB expression is associated with nasopharyngeal, testicular, and breast cancers, suggesting that CRYAB acts as a tumor-suppressor gene." (PMID 34069924, 2021). "In recent years, the role of CRYAB as a marker in tumorigenesis, tumor invasion, and metastasis and prognosis has received increasing attention." (PMID 32595729, 2020). "Ultimately, we performed gene set enrichment analysis (GSEA), protein-protein interaction (PPI) networks, and Bayesian networks (BNs) to explore the underlying mechanisms by which ECM1, CRYAB, CGNL1, and GPX3 are involved in tumor progression." (PMID 32292720, 2020). "The correlation analysis in PCa primary tumor specimens showed that a single gene, Crystallin Alpha B (CRYAB), had a consistent correlation (in more than 50% of datasets) with MITF, both the mean of isoforms and the individual isoform A." (PMID 30310055, 2018). "Furthermore, CAFRI-related genes were differentially expressed in OV tumour tissues, with the exception of CRYAB." (PMID 38057405, 2023). "There is a need for such studies to identify downstream effects of CRYAB expression, identify CRYAB’s tumour-suppressive role in LumA BC, and better determine whether CRYAB is an effector in cytoskeletal organisation or disorganisation." (PMID 36463288, 2022). "Additionally, CRYAB expression significantly correlated with tumor microenvironment (TME), immune checkpoints (ICP), tumor mutational burden (TMB), and microsatellite instability (MSI) in human cancers." (PMID 36713654, 2022). "Alpha B-crystallin (CRYAB or HspB5) gene is located in the tumor-suppressive 11q22-23 region." (PMID 34069924, 2021). "The immunoreactivity of CRYAB was present mainly in the cytoplasm of the tumor cells." (PMID 34069924, 2021).
tumor (continued). "In cancer, CRYAB can act as an oncoprotein or a tumor suppressor." (PMID 33925547, 2021). "On the other hand, TPM1, CASQ2, and CRYAB have low expression in BCa samples, which may indicate that they could serve as tumor suppressors." (PMID 31991631, 2020). "CRYAB’s role in tumor pathogenesis and development has been studied in recent years." (PMID 31152111, 2019). "In addition, we have unveiled CRYAB as a novel direct target of the transcription factor that is, at least in part, responsible for its tumor-suppressive activity in PCa." (PMID 30310055, 2018). "The CRYAB, MYL9, and SORBS1 genes also act as tumor suppressors through involvement in different signaling pathways." (PMID 41439026, 2025). "Furthermore, tumor samples were assessed and classified into four distinct groups based on their mutational load: High TMB with High CRYAB+ GBM score, Low TMB with High CRYAB+ GBM score, High TMB with Low CRYAB+ GBM score, and Low TMB with Low CRYAB+ GBM score." (PMID 38274814, 2023). "The heatmap showed that more than half of the genes were downregulated in tumor tissue, and consistent with the univariate Cox regression analysis, they represented a better prognosis, including PTGS2, ACO1, DPP4, CRYAB, PRKCA, ACSL4 and AKR1C3." (PMID 34475496, 2021). "SPP1, CRYAB, NNMT and HILPDA were highly expressed in tumour cells (ccRCC1); GSTA2, BHMT and ADSSL1 were highly expressed in tumour cells 1 (ccRCC2); and HIF1A-AS2, DNAH11 and EGOT were highly differentially expressed in tumour cells 2 (ccRCC2)." (PMID 34168986, 2021). "Alpha B-crystallin (CRYAB, HSPB5) belongs to the small heat shock protein (HSP) family and is highly expressed in various human cancers, suggesting a crucial role in tumor progression." (PMID 34069924, 2021). "OLFM4, SPINK8, CRYAB, KCNMA1, TFAP2B, and TFF1 were significantly upregulated during tumor progression in P8‐2 CTCs." (PMID 33377642, 2020). "Taken together, these data presented CRYAB as a direct target of MITFA and the best candidate to mediate its tumor-suppressive activity in PCa." (PMID 30310055, 2018). "Additionally, the presence of RNA, which encodes oncogenes or tumor suppressor genes that are characteristically expressed in HNSCC, like SOX2, CRYAB, and PTHLH, further suggests transmission of tumor RNA into platelets." (PMID 37455825, 2023). "In the vasculature, CRYAB is expressed in a subset of human tumor vessels, but not in normal capillaries, and is thought to assist tumor angiogenesis as it promotes survival." (PMID 31757032, 2019). "PTC and FTC tumours presented a group of common dysregulated proteins including SOD3, ISLR, biotinidase, polymerase I and transcript release factor (cavin-1), TFF3, alpha(B)-crystallin (CryAB), AGR2, tenascin and 14-3-3 gamma." (PMID 27025787, 2016). "Indeed, in our IF stainings, both CD44 and CRYAB specifically stained GTCs in both GTC-high and GTC-low tumor samples and the number of CD44+ or CRYAB+ cells were significantly higher in GTC-high tumors (Wilcoxon rank sum test, two-sided; p = 0.00666, p = 0.00524, respectively)." (PMID 39880824, 2025). "In contrast, the tumor core region is enriched with genes related to cell proliferation (such as MKI67), while cells in the invasive margin express high levels of migration-related molecules (such as CD44 and the MMP family) and stress response genes (such as HSPB1/CRYAB)." (PMID 41201287, 2025). "Additionally, CRYAB and CD44 are highly co-expressed in aggressive GBM, synergistically regulating cytoskeletal remodeling and anti-apoptotic signaling pathways, which significantly enhances the tumor's recurrence after surgery." (PMID 41201287, 2025). "Furthermore, ferroptosis-related genes with copy number amplification (including FADS2, NQO1, ABCC1, ACSF2, HMOX1, FANCD2 and SQLE) demonstrated higher expression in tumour tissues, and those with copy number deletion (including CRYAB, ACSL3, ZEB1) demonstrated lower expression in tumour tissues." (PMID 35145965, 2022).
tumor (continued). "Two main groups were identified, one over-expressing markers typically found in sporadic luminal tumours such as GATA3, TFF1 and SCUBE2, and the other negative for ESR1, ERBB2 and the PR gene (PGR) (triple negative) and over-expressing genes from the basal layer such as CDH3, CRYAB and KRT5-17." (PMID 19826428, 2009). "Their trend of expression showed most of them to be upregulated in the tumor samples, regardless of the disease stage, while only PPL, ALDH1A1, GSTA1, TJP3 and CRYAB were downregulated in HNSCC." (PMID 37686696, 2023).
cancer (51 papers, 2011 to 2025). A tumor composed of atypical neoplastic, often pleomorphic cells that invade other tissues. "Abnormal expression of the CRYAB gene in tumors has been extensively studied and is associated with the biological characteristics and prognosis of cancers." (PMID 38274814, 2023). "To explore the possible mechanism underlying the effects of CRYAB on cancer patients, we conducted GO and KEGG enrichment analyses of binding proteins and genes related to CRYAB expression." (PMID 36713654, 2022). "Paradoxically, CRYAB is highly expressed in some cancer types but decreased in others and in both scenarios an association with cancer progression and prognosis has been reported." (PMID 30310055, 2018). "The up-regulation of CRYAB was shown to be associated with several cancers, including renal, breast, thyroid, head and neck, hepatocellular, and nasopharyngeal types." (PMID 30020984, 2018). "Despite multiple studies demonstrating a role for CRYAB in promoting tumorigenesis in vitro, it remains undetermined whether there is a causal link between CRYAB overexpression and cancer formation." (PMID 36624493, 2023). "Besides, CRYAB expression was positively associated with the immune infiltration of cancer-associated fibroblasts (CAFs) and endothelial cells in most human cancers." (PMID 36713654, 2022). "Indeed, CRYAB malfunction has been associated with myopathy, neuropathy, ischemia, cataract, and cancer." (PMID 34069924, 2021). "In a similar vein, the activation of small heat shock proteins (CRYAA, CRYAB, CRYBB1), which are known as protectors against oxidative stress and apoptosis in normal and cancer cells, can be considered as a hallmark of generalized stress resistance." (PMID 41287033, 2025). "The expression of CRYAB has been thoroughly investigated in the context of a wide range of cancers where it has been validated as a prognostic marker." (PMID 36624493, 2023). "Overall, the bioinformatic analysis suggests that CRYAB overexpression leads to poor outcome in several types of cancers and angiogenesis is significantly positively correlated to CRYAB expression in most cancers." (PMID 36624493, 2023). "Intriguingly, top five upregulated genes are all linked to regulation of oncogenesis and metastasis and pan cancer analysis of TCGA dataset revealed that these genes have co-occurrence of expression in cancers including CRYAB with BSG and HELLS." (PMID 36624493, 2023). "In this pan-cancer analysis, we found that CRYAB gene expression was elevated in KIRC through TCGA and GTEx database." (PMID 36713654, 2022). "Herein, we identified the role of the CRYAB gene in human cancers via a pan-cancer analysis of TCGA and CPTAC databases." (PMID 36713654, 2022). "Further, we explored CRYAB gene expression in pan-cancer via the Sangerbox tool using the TCGA and GTEx databases." (PMID 36713654, 2022). "We found that CRYAB expression was different in tumors and adjacent tumors in human cancers, affecting patients’ prognosis in 15 cancer types." (PMID 36713654, 2022). "Pathway enrichment analysis of CRYAB-related genes and CRYAB binding proteins was conducted to understand the mechanisms by which the CRYAB gene regulates cancer cells on a molecular level." (PMID 36713654, 2022). "Subsequently, we examined the relationship between CRYAB gene expression and pathological stages of cancers." (PMID 36713654, 2022). "TIMER2.0 was used to investigate the extent of immune infiltration and CRYAB gene expression in human cancers." (PMID 36713654, 2022). "Further, we examined the relationship between CRYAB gene expression and pathological stages of cancers." (PMID 36713654, 2022). "Analysis of data on pathological stages of cancer revealed a possible connection between high CRYAB expression and advanced pathological staging in CESC, COAD, BLCA, and STAD due to the increased infiltration of CAFs and endothelial cells in the TME." (PMID 36713654, 2022).